CALB1 (calbindin 1)
Description:
Buffers cytosolic calcium. May stimulate a membrane Ca(2+)- ATPase and a 3',5'-cyclic nucleotide phosphodiesterase.
Synonyms: CALB; D-28K
Tractability: PROTAC: ubiquitination databases record sites on it; its protein half-life has been measured.
Gene: Protein-coding gene on chromosome 8 (90,058,608 to 90,095,475, reverse strand). Ensembl gene ENSG00000104327.
Subcellular location (Human Protein Atlas): Vesicles
Pathways (Reactome):
Metabolism of proteins: Amyloid fiber formation
Gene Ontology:
Molecular function: calcium ion binding; protein binding; zinc ion binding; calcium ion binding involved in regulation of postsynaptic cytosolic calcium ion concentration; calcium ion binding involved in regulation of presynaptic cytosolic calcium ion concentration
Biological process: long-term memory; short-term memory; calcium ion homeostasis; cochlea development; learning or memory; metanephric collecting duct development; metanephric connecting tubule development; metanephric distal convoluted tubule development; metanephric part of ureteric bud development; regulation of postsynaptic cytosolic calcium ion concentration; regulation of presynaptic cytosolic calcium ion concentration; regulation of synaptic plasticity; response to auditory stimulus; retina development in camera-type eye; retina layer formation
Cellular component: axon; dendrite; extracellular exosome; neuronal cell body; nucleus; cytosol; synapse; terminal bouton; calyx of Held; cell body; cuticular plate; cytoplasm; GABA-ergic synapse; glutamatergic synapse; hippocampal mossy fiber to CA3 synapse; neuron projection; postsynapse; postsynaptic cytosol; presynaptic cytosol; stereocilium
Genetic constraint (gnomAD): Loss-of-function variants: 5 observed, 17.17 expected, observed/expected ratio (o/e) 0.29, 90% interval 0.15 to 0.61. The upper end of that interval is the gene's LOEUF score, 0.61, which puts it in group 2 of 6, group 1 being the genes least tolerant of losing a copy. Missense variants: 86 observed, 116.75 expected, observed/expected ratio (o/e) 0.74, 90% interval 0.62 to 0.88. Synonymous variants: 43 observed, 49.58 expected, observed/expected ratio (o/e) 0.87, 90% interval 0.68 to 1.12.
Homologues: Orthologues: chimpanzee CALB1 (100% identical), dog CALB1 (99% identical), macaque CALB1 (99% identical), mouse Calb1 (98% identical), rat Calb1 (98% identical), pig CALB1 (98% identical), rabbit CALB1 (98% identical), guinea pig CALB1 (95% identical), tropical clawed frog calb1 (77% identical), zebrafish calb1 (69% identical), Drosophila melanogaster Cbp53E (44% identical). Paralogues in human: CALB2 (59% identical), SCGN (38% identical).
Diseases named in the same sentence as CALB1 in open-access papers:
CALB1 is named in the same sentence as 79 diseases in open-access papers, as found by Europe PMC text mining. Sharing a sentence is not in itself a finding about the gene and the disease. The quoted sentences say what the papers report.
Alzheimer disease (12 papers, 2008 to 2025). A progressive, neurodegenerative disease characterized by loss of function and death of nerve cells in several areas of the brain leading to loss of cognitive function such as memory and language. "Previous research has indicated that CALB1 plays a protective role in the pathogenesis of Alzheimer's disease; its depletion exacerbates neuronal loss, apoptosis, and mitochondrial dysfunction in Alzheimer's disease mouse models." (PMID 39748132, 2025). "For Alzheimer’s disease, it has been reported that CALB1 has protective effects against the pro-apoptotic action of mutant presenilin 1 (PS-1), attenuating the increase in intracellular calcium and aiding in the prevention of impaired mitochondrial function." (PMID 36855067, 2023). "In the APP/PS1 mouse model of Alzheimer’s disease, which shows anxiety-like behaviour, photostimulating the pBLA–vCA1Calb1+ circuit ameliorates the anxiety in a Calb1-dependent manner." (PMID 31924799, 2020). "Patch-like reduction of Calb1 expression in the DG granule cell layer was found in P123H βS Tg mice; a similar phenotype was observed in a mouse model of Alzheimer’s disease (line J20)." (PMID 29976232, 2018). "As for neurodegenerative disorders, recent studies revealed that Alzheimer’s disease mouse model showed a drastic decrease in the expression of Calb1 in adult DG, suggestive of iDG-like phenotype in the mouse model." (PMID 29976232, 2018). "Reduced calbindin 1 immunocytochemical staining has also been demonstrated during normal brain aging in rhesus monkeys and humans, and becomes more pronounced in Alzheimer's disease." (PMID 18830410, 2008).
Parkinson disease (8 papers, 2019 to 2024). A progressive degenerative disorder of the central nervous system characterized by loss of dopamine producing neurons in the substantia nigra and the presence of Lewy bodies in the substantia nigra and locus coeruleus. "Decreases in CALB1 expression/concentration in brain tissue has been associated with neurodegeneration in Alzheimer’s, Parkinson’s, and Huntington’s diseases and in ischemic injury studies." (PMID 36855067, 2023). "Increased expression of CALB1, on the other hand, has been reported to induce neurite growth in dopaminergic neuronal cells, demonstrating its protective role, especially in neurological diseases, such as Parkinson’s disease." (PMID 36855067, 2023). "CALB1, a calcium-binding protein that buffers intracellular Ca2+ to maintain signaling homeostasis, has been demonstrated to be important for memory, and its overexpression has been shown to have neuroprotective effects in a murine Parkinson’s disease (PD) model." (PMID 38428408, 2024). "Notably, it may be a general marker of resilient dopamine neurons as CALB1+ neurons in the SNc show relative sparing in Parkinson’s disease." (PMID 34305528, 2021).
lung cancer (6 papers, 2020 to 2024). A malignant neoplasm involving the lung. "Calbindin 1 suppresses apoptosis in tumor cells, potentially worsening outcomes, but is also linked to better survival and resection success in lung cancer." (PMID 38928369, 2024). "CALB1 is overexpressed in nonsmall cell lung cancer (NSCLC) tissues, and has a significant connection with lymph node metastasis and prediction of worse survival." (PMID 36618366, 2022). "Conversely, miR-454-3p was also observed to act as a tumor suppressor in bladder cancer and non–small cell lung cancer by targeting the EMT inducer ZEB2 or constituent Ca2+-binding protein calbindin 1 (CALB1), respectively." (PMID 34017681, 2021). "However, CALB1 expression is reported to correlate with improved survival of patients with lung cancer, contradicting with reports that suggested an association of CALB1 upregulation with cancer stemness in meningiomas and senescence inhibition in ovarian cancer." (PMID 33298014, 2020). "To investigate changes of PMCs, we evaluated the transcriptomes of PMCs (CALB1, WT1, and UPK3B-positive cells) in pleural effusion from patients with congestive heart failure or patients with lung cancer." (PMID 37649596, 2023). "Besides no record about SCN8A, THPA confirmed a similar tendency for an increased expression of HDAC1, DLG1, EPHB2 and CALB1, while GDNF was not apparently changed in either normal or lung cancer tissues; no data were available for SCN8A." (PMID 32102656, 2020).
Anxiety (5 papers, 2020 to 2022). Intense feelings of nervousness, tension, or panic often arise in response to interpersonal stresses. "Calb1 knockdown in the vCA1 abolishes the anxiolytic effect of the pBLA-vCA1 circuit, and thus, both the input specificity and the Calb1 levels determine the specific circuit-associated amelioration of anxiety." (PMID 35211169, 2022). "Therefore, both input specificity and Calb1 levels determine the pBLA–vCA1Calb1+ circuit-associated amelioration of anxiety and memory deficits in AD mice." (PMID 31924799, 2020). "In the APP/PS1 mouse model of AD, showing anxiety-like behavior, the photo stimulating the pBLA-vCA1 circuit ameliorated the anxiety in a Calb1-dependent manner." (PMID 35637434, 2022). "To explore the role of Calb1 in the anxiolytic effect of the pBLA–vCA1 circuit, we microinjected adeno-associated virus (AAV)-shCalb1 or the control AAV-shNT (encoding a nontargeting shRNA) into the vCA1 of wild-type mice and measured anxiety behaviours." (PMID 31924799, 2020). "We also found a highly differential protein network between the aBLA and pBLA, with disorganised firing of a/pBLA–vCA1 inputs in APP/PS1 mice, and the optogenetic stimulation of the pBLA–vCA1Calb1+ circuit attenuated anxiety behaviours and spatial memory deficits in a Calb1-dependent manner." (PMID 31924799, 2020).
ovarian carcinoma (5 papers, 2020 to 2024). A malignant neoplasm originating from the surface ovarian epithelium. "However, few previous studies reported that a higher amount of CALB1 mRNA promoted the proliferation and colony formation of ovarian cancer cells by inhibiting senescence." (PMID 37887755, 2023).
Ataxia (4 papers, 2016 to 2024). Ataxia refers to impaired coordination of voluntary muscle movement. "It is noteworthy that Itpr1, Calb1, Mtss1, and Kcnma1 are known to cause ataxia when mutated in human or mouse models." (PMID 38673939, 2024). "CALB1 is of particular interest in NPC1 since it is highly expressed in cerebellar Purkinje neurons, the loss of which underlie the cerebellar ataxia which is a predominant symptom in NPC1." (PMID 36721240, 2023). "We have previously demonstrated, in a different rodent model of cerebellar ataxia, that the expressions of Calb1, Pcp2 and Grid2, as well as that of some other genes highly expressed in PCs, significantly reduce as the disease phenotype progresses." (PMID 27013529, 2016). "Interestingly, among the 24 PC genes with restored expression, seven genes (Abr, Calb1, Htr1b, Itpr1, Kcnip1, Kcnma1, and Mtss1) were part of a group of 80 PC-type-specific downregulated genes common to the SCA1, SCA2, and SCA7 mouse models and composed an ataxia molecular signature." (PMID 38673939, 2024).
Cognitive impairment (4 papers, 2022 to 2026). Abnormal cognition is characterized by deficits in thinking, reasoning, or remembering. "Targeting Calb1 to modulate pathway transmission may result in cognitive impairment." (PMID 39635132, 2024).
diabetic nephropathy (2 papers, 2019 to 2020). "Other potential biomarkers for diabetic nephropathy include miR-21-5p, miR-15b, miR-34a, miR-636, MASP2, CALB1, myeloblastin, elafin, cystatin B, and neutrophil gelatinase-associated lipocalin, all of which increase in the presence of the condition." (PMID 32849923, 2020).
non-small cell lung carcinoma (2 papers, 2023 to 2024). A group of at least three distinct histological types of lung cancer, including non-small cell squamous cell carcinoma, adenocarcinoma, and large cell carcinoma. "In non-small cell lung cancer, the high expression of CALB1 has a significant correlation with the lymph node metastasis stage." (PMID 38443703, 2024).
prostate carcinoma (2 papers, 2023). A carcinoma that arises from epithelial cells of the prostate gland. "A chimeric transcript between this HERVH provirus and CALB1 was cloned from the prostate cancer cell line PC3 over 30 years ago." (PMID 37192000, 2023). "There were also 5 KLF5K369Q-downregulated and NTZ-upregulated genes whose lower expression levels in human prostate cancers were also significantly associated with worse overall survival, including TMPRSS2, CALB1, SPOCK2, COL4A4, and COL4A3." (PMID 36810084, 2023).
viral infection (2 papers, 2024 to 2025). "Three weeks after viral infection and TMP treatment, DTR-GFP was detected in 55-70% of PSN7 neurons (Calb1+WGA+), and three days after subsequent systemic delivery of DT, no DTR-GFP expressing PSNs were detected in the ganglia, with a single exception." (PMID 41292845, 2025).
adenoma (1 paper, 2020). A neoplasm arising from the epithelium. "Interestingly, CYP3A5 together with CALB1, DAPL1 and FZD9 were recently reported to be enriched in human ACTH-secreting adenomas compared to other pituitary adenomas." (PMID 32183012, 2020).
age (1 paper, 2023). A temporal measurement of the time period elapsed since an identifiable point in the life cycle of an organism. "In light of recent data incriminating ERE derepression as the trigger of both cancer and age-related inflammation, HERVH-driven CALB1 expression may represent a cooption of one retroelement in countering the collective action of many others." (PMID 37192000, 2023).
endometrial cancer (1 paper, 2011). Primary or metastatic malignant neoplasm involving the endometrium (mucous membrane that lines the endometrial cavity). "Calb1 and galectin-1 are two putative MTDH downstream genes that may regulate the metabolism of phosphatidylinositol, which is part of the PI3K/AKT signaling pathway commonly upregulated in endometrial cancer." (PMID 21687633, 2011).
ependymoma (1 paper, 2016). A WHO grade II, slow growing tumor of children and young adults, usually located intraventricularly. "Poor prognostic features were found in two other patients: low expression of PAX8, FHIT, CASP10, CHD2, with high expression of CHD11, FUS, and MTA1 in a patient with Ewing sarcoma, and gain of 1q and loss of 6q and overexpression of TNC, CALB1, PLAG1, ALDH1L1, and RELN in a patient with ependymoma." (PMID 28007021, 2016).
epileptic seizures (1 paper, 2024). "In contrast, Dsp knockdown increased the expression of the mature neuronal markers Calb1, Tdo2, and Ntf3, which are negatively regulated by strong neuronal activation, such as in the ECS and epileptic seizures." (PMID 39176381, 2024).
Hodgkins lymphoma (1 paper, 2025). A heterogeneous group of malignant lymphoid neoplasms of B-cell origin characterized histologically by the presence of Hodgkin and Reed-Sternberg (HRS) cells in the vast majority of cases. "Instances of such onco-exaptation events include the elevated expression of CSF1R and IRF5 in Hodgkin’s lymphoma, the ectopic expression of CALB1 (encoding calbindin) in squamous lung cancer, and the creation of an oncogenic form of ALK (anaplastic lymphoma kinase) in melanoma." (PMID 40336011, 2025).
Hypocalcemia (1 paper, 2012). An abnormally decreased calcium concentration in the blood. "Dietary deficiencies in Vitamin D3 affect Calbindin (Calb1) expression in ameloblasts and odontoblasts in rat incisors leading to hypocalcemia and dentin hypomineralization." (PMID 22866057, 2012).
Insulin resistance (1 paper, 2025). Increased resistance towards insulin, that is, diminished effectiveness of insulin in reducing blood glucose levels. "Interestingly, despite the high expression of CALB1, CaBP-D9K, and ECAC1 in insulin resistance, their lower protein conversion rates suggest that these proteins may function independently of vitamin D-related mechanisms." (PMID 39906623, 2025).
kidney injury (1 paper, 2025). Trauma to the kidney. "Calbindin 1, clusterin, GSTP1, KIM-1, and MCP-1 concentrations in maternal plasma could be used in the monitoring of kidney injury in preeclamptic women; however, there is a need to perform longitudinal studies." (PMID 40649927, 2025).
lung squamous cell carcinoma (1 paper, 2025). "Additionally, in lung squamous cell carcinoma (LUSC), the production of chimeric transcripts driven by HERVH and a neighboring gene from the calbindin 1 (CALB1) locus correlates with improved patient survival." (PMID 40618134, 2025).
metabolic syndrome (1 paper, 2020). A cluster of metabolic risk factors for CARDIOVASCULAR DISEASES and TYPE 2 DIABETES MELLITUS. "DNA microarray analysis was used to investigate the kidney expression of four genes (Cyp24a1, Plin2, Calb1 and Usp2), which are reported to be involved in metabolic syndrome and LSRD." (PMID 33383715, 2020).
osteosarcoma (1 paper, 2022). A usually aggressive malignant bone-forming mesenchymal neoplasm, predominantly affecting adolescents and young adults. "In osteosarcoma, the downregulation of CALB1 gene expression resulted in reduced cell proliferation and cell clonal formation." (PMID 36618366, 2022).
preeclampsia (1 paper, 2025). Preeclampsia is a hypertensive disorder of pregnancy that is characterized by new-onset hypertension with proteinuria presenting after 20 weeks of gestation, and depending on mild or severe forms may initially present with severe headache, visual disturbances, and hyperreflexia. "The results revealed that five out of the six serum biomarkers of kidney injury were elevated in the preeclampsia group compared to the control group (calbindin 1, clusterin, glutathione transferase pi (GSTP1), monocyte chemotactic protein 1 (MCP-1), and kidney injury molecule type 1 (KIM-1))." (PMID 40649927, 2025). "Additionally, the serum concentrations of calbindin 1, clusterin, GSTP1, and KIM-1 were significantly higher in both early-onset and late-onset preeclampsia compared to the control group." (PMID 40649927, 2025).
vascular dementia (1 paper, 2023). A degenerative vascular disorder affecting the brain. "The activation of Calb1, a calcium-binding protein widely expressed in neurons, increased neuronal viability and reduced neuronal apoptosis in vascular dementia rats." (PMID 37765280, 2023).